CUL4A (cullin 4A)
Diseases named in the same sentence as CUL4A in open-access papers (continued):
Sharing a sentence is not in itself a finding about the gene and the disease.
mesothelioma (continued). "Moreover, our results revealed that mTOR pathway is involved in Cul4A-mediated Gli1 expression in mesothelioma cells, possibility through mTOR activation by Cul4A-mediated proteolysis of mTOR inhibitors and through crosstalk between the activated mTOR pathway and Gli1 pathway." (PMID 26218750, 2015). "This may be an underestimate, given that (i) FISH analysis of clinical tissue sections was done in interphase, (ii) visualizing the locations of FISH probes in clinical tissue sections is difficult and (iii) 6/6 of mesothelioma cell lines showed increased Cul4A copy number (3–4 copies) by FISH." (PMID 26218750, 2015). "Our results showed a 72.2% concurrency of increased Cul4A copy number and Cul4A protein overexpression in the identical mesothelioma patient samples, suggesting that the increased Cul4A copy number may contribute to the increased Cul4A expression in the mesothelioma tumours." (PMID 26218750, 2015). "Among the 72 mesothelioma samples analysed (excluding one missing sample), Cul4A staining was negative in 9.7%, weak in 19.4% and moderate to strong in 70.9%." (PMID 26218750, 2015). "Among the six mesothelioma samples with negative Cul4A expression, one showed negative Gli1 expression and two showed weak Gli1 expression." (PMID 26218750, 2015). "Among 14 mesothelioma samples with weak Cul4A expression, 28.6% showed negative Gli1 expression and 50% showed weak Gli1 expression." (PMID 26218750, 2015). "Similar to our observations in mesothelioma tumours, six mesothelioma cell lines that had increased Cul4A copy number detected using FISH showed moderate to strong Cul4A staining by IHC, suggesting that increased Cul4A copy number may contribute to increased Cul4A expression in these cell lines." (PMID 26218750, 2015). "We have also observed decreased transcriptional activities of SMO and Gli1 in mesothelioma H28 cells after Cul4A knockdown by siRNA (data not shown), suggesting that SMO is in part involved in the Cul4A-mediated Gli1 expression." (PMID 26218750, 2015).
Multiple Myeloma (3 papers, 2015 to 2021). "Although the molecular mechanisms underlying the anti-myeloma activity of IMiDsR have been reported to involve the Cullin 4A (CUL4A)- Cereblon (CRBN) E3 ligase complex mediated proteasomal degradation of downstream targets." (PMID 33014791, 2020).
nasopharyngeal carcinoma (3 papers, 2019 to 2022). A carcinoma arising from the nasopharyngeal epithelium. "Association between CUL4A expression and clinicopathological variables in nasopharyngeal carcinoma patients." (PMID 31860954, 2019). "This study aimed to analyze the expression of CUL4A in nasopharyngeal carcinoma (NPC) tissues and the associations of CUL4A expression with prognostic significance." (PMID 31860954, 2019).
breast tumors (2 papers, 2009 to 2014). "In previous studies we showed that the overexpression of CUL4A was associated with markers of proliferation and tumor aggressiveness in familiar and sporadic primary breast tumors." (PMID 24870930, 2014). "One of the mechanisms triggering CUL4A overexpression is the 13q34 amplification and this genomic aberration has been shown to be associated with breast tumors characterized by exhibiting BRCA1 impairment or a basal-like phenotype." (PMID 24870930, 2014). "This dependence or ‘addiction’ to CUL4A for maintenance of the malignant phenotype and cell survival of CUL4A-overexpressing cells would be similar to that observed in breast tumor cells that overexpress ERBB2 or C-MYC." (PMID 24870930, 2014). "We provide evidence that, rather than being a passenger alteration derived from the increased genomic instability shown by basal-like and BRCA1 primary breast tumors, CUL4A overexpression would confer selective advantage to tumor cells." (PMID 24870930, 2014). "With these antecedents we were interested in studying the role of CUL4A in the carcinogenic process of the basal-like breast tumor subtype, which is aggressive in nature and lacks effective targeted therapies." (PMID 24870930, 2014). "Furthermore, our results suggest the role for CUL4A as part of the development of breast tumors in general, mainly through deregulation of cell cycle checkpoints." (PMID 19995430, 2009). "Our results support a potential synergistic effect between CUL4A overexpression and the constitutive activation of the RAS mitogenic signal in the transformation of human mammary epithelial cells, which is consistent with the high frequency of RAS pathway activation in basal-like breast tumors." (PMID 24870930, 2014). "However, the specific contribution of CUL4A to the biology of basal-like breast tumors has not yet been elucidated." (PMID 24870930, 2014).
cardiac hypertrophy (2 papers, 2016 to 2020). "Intriguingly, loss of cullin-4A-dependent Grk2 regulation in cullin-4A knockout mice is linked to a sex-dimorphism: only male mice are affected by cardiac hypertrophy." (PMID 33114658, 2020). "The cardiac hypertrophy defect seen in Cul4a−/− mice can be partially rescued by deletion of one allele of Grk2." (PMID 27462452, 2016). "However, cullin-4A knockout mice develop a cardiac phenotype characterized by increased hypertension, weakened heart function, and cardiac hypertrophy in male mice only." (PMID 33114658, 2020). "We previously characterized Cul4a null mice and found that, although overall appearing to development normally, the male, but not female Cul4a−/− mice develop cardiac hypertrophy." (PMID 27462452, 2016).
Colon Cancer (2 papers, 2017 to 2025). "Previous studies have shown that inflammation-induced Jak-STAT3 signaling triggers the ubiquitination of DICER1 in cytoplasm by CUL4A to promote the development of colon cancer." (PMID 28420424, 2017).
glioblastoma (2 papers, 2021 to 2023). The most malignant astrocytic tumor (WHO grade IV). "Since no SOX2-targeting E3 ubiquitin ligase has yet been identified in glioblastoma cells, we tested the role of four E3 ubiquitin ligases (CDH1-APC, CUL4A, UBR5, and WWP2) which have been demonstrated to target SOX2 in other cellular contexts through an RNA interference-based approach in GSCs29–32." (PMID 34732716, 2021).
ovarian tumor (2 papers, 2014 to 2019). "Elevated expression of CUL4A is correlated with significantly shorter overall survival and accelerated neoplastic transformation in ovarian tumors and node-negative breast cancers suggesting that elevated expression of CUL4A may promote carcinogenesis." (PMID 25421893, 2014).
skin cancer (2 papers, 2014 to 2017). "In recent years, the potential therapeutic value of directly targeting CUL4A was also put forth by researchers, e.g., inhibition of CUL4A ubiquitin ligase was found to prevent UV-associated skin cancer and premature aging." (PMID 28576144, 2017). "CRL4 activity is also required for the NER pathway by controlling the detection and processing of DNA lesions induced by UV in plants, but also in mammals, as loss of CUL4A in mice leads to an increase in susceptibility to UV skin cancer." (PMID 25116939, 2014).
atherosclerosis (1 paper, 2026). A disease characterized by the build-up of fatty material and calcium deposition in the arterial wall resulting in partial or complete occlusion of the arterial lumen. "Our data further demonstrate that, in response to atherosclerosis-related stimuli, CUL4A, DDB1, and CRBN undergo marked cytoplasmic translocation in endothelial cells, leading to increased formation of cytoplasmic CRL4ACRBN complexes." (PMID 41424849, 2026).
chronic obstructive pulmonary disease (1 paper, 2019). A chronic and progressive lung disorder characterized by the loss of elasticity of the bronchial tree and the air sacs, destruction of the air sacs wall, thickening of the bronchial wall, and mucous accumulation in the bronchial tree. "The expression of CUL4A was assessed by immunohistochemistry in lung epithelium specimens from smokers, non-smokers and patients with chronic obstructive pulmonary disease." (PMID 31060565, 2019). "In this study, we found that the expression of distal respiratory epithelial CUL4A increased in smokers and patients with the COPD compared with nonsmokers, especially in patients with chronic obstructive pulmonary disease." (PMID 31060565, 2019).
gastric tumors (1 paper, 2016). "In contrast, in gastric tumors, higher levels of CUL4A protein were detected (68/124; 55%), and CUL4A was distributed nucleocytoplasmically." (PMID 26840256, 2016). "Higher levels of CUL4A protein in gastric tumors compared to normal gastric mucosa were also observed by immunohistochemistry." (PMID 26840256, 2016). "Moreover, as determined by western blotting, CUL4A protein levels were higher in gastric tumors than in adjacent noncancerous gastric tissues (n=4)." (PMID 26840256, 2016).
glioma (1 paper, 2023). A benign or malignant brain and spinal cord tumor that arises from glial cells (astrocytes, oligodendrocytes, ependymal cells). "To further confirm that S100A16 regulates LATS1 protein levels through CUL4A-mediated ubiquitination, we transfected CUL4A siRNA or cDNA into glioma cells pre-treated with MG132." (PMID 37151881, 2023).
HCMV infection (1 paper, 2020). "As a control, the level of p21CIP1, which is degraded by the CUL4-associated CRL complex, was less effectively reduced by HCMV infection in CUL4A-depleted cells." (PMID 32850489, 2020).
ischemia (1 paper, 2016). A hypoperfusion of the BLOOD through an organ or tissue caused by a PATHOLOGIC CONSTRICTION or obstruction of its BLOOD VESSELS, or an absence of BLOOD CIRCULATION. "Interestingly the overexpression of the ubiquitin E3 ligase gene (CUL4A), found to have differential ASE in our ischemia model, has been found to suppress apoptosis and DNA damage in experimental pheochromocytoma model of ischemia-reperfusion." (PMID 27923400, 2016).
leukemia (1 paper, 2016). A malignant (clonal) hematologic disorder, involving hematopoietic stem cells and characterized by the presence of primitive or atypical myeloid or lymphoid cells in the bone marrow and the blood. "In contrast, CUL4A, a core component of a cullin-based E3 ubiquitin ligase complex and overexpressed in cancer, and PCM1, a centrosome binding protein translocated to the JAK2 locus in certain leukemias, both bound uniquely in α7HMZ colons." (PMID 27166517, 2016).
lung squamous cell carcinoma (1 paper, 2020). "Our previous study showed that CUL4A and CUL4B had a strong association with tobacco smoking risk in lung squamous cell carcinoma (SCC) and small cell lung carcinoma (SCLC)." (PMID 32587774, 2020).
lymph node metastasis (1 paper, 2016). "We showed that CUL4A protein expression was significantly correlated with lymph node metastasis in GC patients." (PMID 26840256, 2016). "In the present study, we report that the expression of CUL4A significantly correlated with the clinical stage of the tumor and lymph node metastasis, and survival rates were lower in GC patients with higher levels of CUL4A than in patients with lower CUL4A levels." (PMID 26840256, 2016). "In our study, we found that the expression of CUL4A significantly correlated with GC patients' TNM classification and lymph node metastasis." (PMID 26840256, 2016).
melanoma (1 paper, 2018). A malignant, usually aggressive tumor composed of atypical, neoplastic melanocytes. "For example, CUL4A is highly expressed in many types of cancer, and it increases the survival of melanoma cells exposed to UV radiation by promoting nucleotide excision repair." (PMID 30018425, 2018).
mood disorder (1 paper, 2021). A cognitive disorder a disturbance in which the person's mood is hypothesized to be the main underlying feature. "Therefore, the differential G-to-A RNA editing in Cul4a were probably in line with a potential role of the gene in emotional stress and mood disorders." (PMID 34093668, 2021).
Obesity (1 paper, 2025). Accumulation of substantial excess body fat. "Damage to CSN/CUL3/CUL4A genes is associated with diverse diseases, including obesity." (PMID 40149914, 2025). "Patients possessing 13q34 microdeletions, the localization of the CUL4A gene, display clinical features including intellectual disability, mild facial dysmorphism, and obesity." (PMID 40149914, 2025).
osteoporosis (1 paper, 2024). A condition of reduced bone mass, with decreased cortical thickness and a decrease in the number and size of the trabeculae of cancellous bone (but normal chemical composition), resulting in increased fracture incidence. "E3 ubiquitin ligase CUL4A promoted osteoclast differentiation and osteoporosis by upregulating ZEB1 to repress miR-340-5p expression, causing HMGB1 upregulation and the TLR4 activation." (PMID 38504994, 2024).
sarcoma (1 paper, 2020). A usually aggressive malignant neoplasm of the soft tissue or bone. "High expression levels of CUL4A were associated with better PFS for trabectedin in nontranslocation-related sarcomas; however, protein expression analysis showed an unexpected association between worse PFS and cases with high expression of CUL4A in our series." (PMID 32365979, 2020).
viral infection (1 paper, 2015). "It remains to be seen whether mammalian Cul4A/B act in a similar manner during viral infection." (PMID 26325027, 2015).
cancer (60 papers, 2009 to 2025). A tumor composed of atypical neoplastic, often pleomorphic cells that invade other tissues. "Several genes located in 13q34 have been associated with a worse prognosis in other cancers, including CUL4A and TFDP1, IRS2 and CDC16." (PMID 35887382, 2022). "Growing evidence has shown that Sp1 and CUL4A are both overexpressed in many cancers and are associated with a poor prognosis." (PMID 33895141, 2021). "Of the eight Cullins, the underlying mechanisms of CUL4A in the pathogenesis of cancer are most characterized." (PMID 29377600, 2018). "CUL4A overexpression in cancer is associated with tumor size, cell proliferation, migration, invasion, and cancer aggressiveness." (PMID 29594129, 2018). "Recent data support that the high expression of CUL4A is associated with adverse clinical outcomes in several cancer types, including breast, lung, and bone cancer." (PMID 26840256, 2016). "Overexpression of CUL4A/B has been demonstrated in many types of cancers, and is associated with a poor prognosis of patient survival." (PMID 26460955, 2015). "In tumours, CRL4 has been shown to be dysregulated mainly due to overexpression of the CUL4A/B scaffold proteins, making it an attractive anti‐cancer target." (PMID 39856363, 2025). "We also assessed 7 cancer cell lines with different CUL4A and B expressions and observed an inverse correlation between CUL4 protein levels and SN38 sensitivity, indicating CUL4 proteins as potential predictive biomarkers for TOP1 inhibitors." (PMID 37353483, 2023). "CUL4A overexpression has been detected in various types of cancers, such as breast and lung cancers, present in ≈63% of the total malignant cases, and is negatively correlated with patients’ prognosis." (PMID 33627782, 2021). "In cancer cells, Cul4a and Cul4b have been shown to regulate proliferation, DNA damage and repair, cell cycle progression, DNA methylation and histone acetylation, as well as cell signaling." (PMID 33524014, 2021). "Overexpression of CUL4A or CUL4B is a very common sign in many types of cancers in which CUL4A or CUL4B proteins conservatively interacts with DDB1 to recruit other proteins such as RBXs and DACFs, assembling CRL4 E3 ligases 14-19." (PMID 32140073, 2020). "Previous studies showed that CUL4A played a functional role in metastasis in cancer cells by inducing proliferation, EMT, migration, and invasion." (PMID 31409387, 2019). "We further explored the expression of the cancer metastasis suppressor ANXA10 after knocking down Cul4A." (PMID 31052599, 2019). "As a result, Cul4A plays important roles in oncogenesis and it is an attractive target for cancer therapy." (PMID 31052599, 2019). "CUL4A is broadly expressed in many cancer types, including breast cancer and hepatocellular carcinoma." (PMID 29377600, 2018). "To determine the effects of CUL4A on the mobility of cancer cells, we established two stably CUL4A-overexpressing cell lines, designated as SSP-25-CUL4A and RBE-CUL4A." (PMID 28576144, 2017). "In recent years, accumulating research data have demonstrated that CUL4A is overexpressed in multiple human cancers and contributes to tumor progression and metastasis, resulting in poorer survival rates of cancer patients." (PMID 28576144, 2017). "With increasing knowledge, development of iCCA anti-cancer therapy targeting CUL4A can be expected in the near future." (PMID 28576144, 2017). "CUL4A is amplified in various cancers, which suggests its role in regulating cell cycle progression, transcription, and embryonic development." (PMID 28420424, 2017). "Given the wide variety of cellular phenotypes that these protein substrates influence, such as proliferation and DNA repair, CUL4A has been proposed as a possible cancer driver and drug target." (PMID 27149990, 2016). "Although several studies have investigated the function of CUL4A in different cancer types, less is known about the mechanisms that regulate CUL4A expression." (PMID 26840256, 2016).